NET1 (neuroepithelial cell transforming 1)
Description:
Acts as a guanine nucleotide exchange factor (GEF) for RhoA GTPase. May be involved in activation of the SAPK/JNK pathway Stimulates genotoxic stress-induced RHOB activity in breast cancer cells leading to their cell death.
Synonyms: ARHGEF8; NET1A
Tractability: PROTAC: ubiquitination databases record sites on it.
Gene: Protein-coding gene on chromosome 10 (5,412,557 to 5,459,056, forward strand). Ensembl gene ENSG00000173848.
Subcellular location: Cytoplasm; Nucleus
Subcellular location (Human Protein Atlas): Nucleoplasm; Vesicles
Pathways (Reactome):
Signal Transduction: G alpha (12/13) signalling events; NRAGE signals death through JNK; RHOA GTPase cycle; RHOB GTPase cycle
Gene Ontology:
Molecular function: protein binding; guanyl-nucleotide exchange factor activity
Biological process: cellular response to hydrogen peroxide; cellular response to ionizing radiation; positive regulation of apoptotic process; positive regulation of GTPase activity; positive regulation of Rho protein signal transduction; regulation of cell growth; regulation of small GTPase mediated signal transduction; signal transduction; intracellular signal transduction
Cellular component: cytosol; cytoplasm; nucleus
Genetic constraint (gnomAD): Loss-of-function variants: 37 observed, 47.2 expected, observed/expected ratio (o/e) 0.78, 90% interval 0.6 to 1.03. The upper end of that interval is the gene's LOEUF score, 1.03, which puts it in group 4 of 6, group 1 being the genes least tolerant of losing a copy. Missense variants: 607 observed, 679.77 expected, observed/expected ratio (o/e) 0.89, 90% interval 0.83 to 0.95. Synonymous variants: 234 observed, 257.33 expected, observed/expected ratio (o/e) 0.91, 90% interval 0.82 to 1.01.
Homologues: Orthologues: macaque NET1 (97% identical), chimpanzee NET1 (97% identical), rabbit NET1 (89% identical), guinea pig NET1 (88% identical), dog NET1 (87% identical), rat Net1 (86% identical), pig NET1 (78% identical), mouse Net1 (76% identical), tropical clawed frog net1 (69% identical), zebrafish net1 (60% identical), Caenorhabditis elegans prhg-1 (16% identical), Drosophila melanogaster cyst (15% identical). Paralogues in human: ARHGEF3 (47% identical), ARHGEF11 (22% identical), ARHGEF12 (21% identical), ARHGEF28 (20% identical), ARHGEF1 (19% identical), ARHGEF18 (16% identical), ARHGEF2 (16% identical), PLEKHG6 (14% identical).
Diseases named in the same sentence as NET1 in open-access papers:
NET1 is named in the same sentence as 52 diseases in open-access papers, as found by Europe PMC text mining. Sharing a sentence is not in itself a finding about the gene and the disease. The quoted sentences say what the papers report.
breast carcinoma (15 papers, 2011 to 2025). "Related research has demonstrated that the NET1-associated eRNA (NET1e) could upregulate the expression of its target gene and promote breast cancer progression." (PMID 34238250, 2021). "Because of the importance of PI3K signaling to human breast cancer, we then assessed whether Net1 activation was associated with PI3K activity." (PMID 29769144, 2018). "The hsa‐miR‐22‐3p promotes chemoresistance by targeting Neuroepithelial Cell Transforming 1 (NET1) in breast cancer, while it enhances chemosensitivity to cisplatin through the PTEN/PI3K/Akt pathway in gastrointestinal stromal tumor cell lines." (PMID 40444136, 2025). "For example, NET1 eRNA regulates the expression of neuroepithelial cell transforming 1 (NET1) oncogene to promote tumorigenesis in breast cancer and HPSE eRNA regulates the expression of heparinase (HPSE) to promote the invasion and metastasis of cancer." (PMID 38602568, 2024). "Neuroepithelial cell transforming gene 1 (NET1), a member of the guanine nucleotide exchange factor family, is involved in various cancers, including gastric cancer, breast cancer and glioma." (PMID 33839702, 2021). "NET1 has been discovered as a significant indicator of poor clinical prognosis of several cancers, including breast cancer, glioma and adenocarcinoma of the oesophagogastric junction (AOG)." (PMID 33839702, 2021). "The high expression of NET1e, an eRNA located about 90 kb downstream of the oncogene NET1, was detected in breast cancer, and NET1e knockdown significantly reduced the proliferation of the breast cancer cell line MCF7." (PMID 34073237, 2021). "Therefore, overexpression of NET1 was closely related to malignant cellular biological behaviors and was also associated with a variety of human cancers, including acute lymphoblastic leukemia, breast cancer, hepatocellular carcinoma, and non-small-cell lung cancer." (PMID 32420320, 2020). "Using a gene expression signature indicative of Net1 activity, we show that Net1 signaling is activated in 10% of human breast cancers, and that this correlates with elevated proliferation and PI3K pathway activity." (PMID 29769144, 2018). "Future work will be required to dissect the components of the Net1 gene expression signature that are conserved among different breast cancer models." (PMID 29769144, 2018). "For example, we observed that a high Net1 gene expression signature correlated closely with human basal-type breast cancers." (PMID 29769144, 2018). "We have observed previously in human breast cancer cells that Net1 controls RhoA activation and actomyosin contractility." (PMID 29769144, 2018). "Net1 contributes to breast cancer progression through multiple mechanisms, which include promotion of cancer cell proliferation and motility, and tumor angiogenesis." (PMID 29769144, 2018). "The subtype independence of Net1 has important implications for therapeutic approaches, as it suggests that targeting Net1 would be a widely applicable therapeutic strategy for breast cancer." (PMID 29769144, 2018). "The RhoA activating protein Net1 contributes to breast cancer cell proliferation, motility, and invasion in vitro, yet little is known about its roles in mammary gland tumorigenesis and metastasis." (PMID 29769144, 2018). "We also demonstrate that human breast cancer patients with a high Net1 gene expression signature experience shorter distant metastasis-free survival." (PMID 29769144, 2018). "We observed that patients with a high Net1 gene expression signature experienced reduced distant metastasis-free survival in a breast cancer dataset, consistent with the requirement for Net1 expression for metastasis in MMTV-PyMT mice." (PMID 29769144, 2018). "We have shown previously that Net1 is required for human breast cancer cell motility and invasive capacity in vitro." (PMID 29769144, 2018).
breast carcinoma (continued). "To perform an unbiased analysis of the mechanism by which Net1 controls PyMT-stimulated tumorigenesis and metastasis, we analyzed global gene expression in wild-type and Net1−/− PyMT mammary tumors." (PMID 29769144, 2018). "Their study showed that reduction of Net-1 signaling inhibits metastasis in a mouse model of lung colonization of a mammary cancer cell line, as well as in a model of lung metastasis in xenografted human breast tumors." (PMID 21672235, 2011). "Net1, a RhoA subfamily guanine‐nucleotide exchange factor, is primarily involved in the proliferation, migration and differentiation of several types of cancer cells, including gastric, lung and breast cancer." (PMID 39675772, 2025). "Knocking out Net1 in breast cancer cells reduces tumour cell proliferation and promotes cell apoptosis, while up‐regulation of NET1 reverses the inhibition of baicalin on the proliferative and invasive capacity of lung cancer cells and enhances acute lymphoblastic leukaemia cell proliferation." (PMID 39675772, 2025). "NET1e appears to contribute to breast cancer progression by up-regulating NET1 expression." (PMID 34073237, 2021). "Moreover, we demonstrate that high Net1 signaling correlates with increased human breast cancer metastasis, indicating that our findings are relevant to human disease progression." (PMID 29769144, 2018). "Together these data indicate that Net1 is required for breast cancer progression in the MMTV-PyMT mouse model and may also contribute to human breast tumorigenesis and metastasis." (PMID 29769144, 2018). "However, the wide incidence of the Net1 gene expression signature in human breast cancers suggests that Net1 function is not limited to this breast cancer subtype." (PMID 29769144, 2018). "When we assessed whether Net1 is activated in particular subtypes of breast cancer, we observed an increased incidence of a positive Net1 gene expression signature in basal-type breast cancers." (PMID 29769144, 2018). "Gene expression in wild-type and Net1 KO tumors was analyzed by gene ontology enrichment and for relative activation of gene expression signatures indicative of signaling pathways important for breast cancer initiation and progression." (PMID 29769144, 2018). "We observed that 10% of all human breast cancers exhibited a high Net1 gene expression signature." (PMID 29769144, 2018). "We then examined whether a high Net1 gene expression signature correlated with distant metastasis-free survival in human breast cancer patients." (PMID 29769144, 2018). "Similarly, the role of Net1 in human breast cancer is largely unknown." (PMID 29769144, 2018). "The neuroepithelial transforming gene 1 (Net1) is a RhoA subfamily GEF that is overexpressed in many human cancers, including breast cancer." (PMID 29769144, 2018). "Net1e eRNA, which is located downstream of NET1 proto-oncogene, is a breast cancer specific eRNA and its knockdown by LNA (locked nucleic acids) antisense RNA was shown to strongly reduce cell proliferation in the MCF7 breast cancer cell line." (PMID 36287118, 2022). "Taken together, these data indicate that a Net1 gene expression signature is observed in highly proliferative breast tumors that harbor elevated PI3K signaling and tend to metastasize sooner, consistent with an important role for Net1 in disease progression in human breast cancer patients." (PMID 29769144, 2018).
gastric cancer (9 papers, 2006 to 2023). A primary or metastatic malignant neoplasm involving the stomach. "Using a luciferase reporter assay, the shorter isoforms of NET1 were seen to exhibit a strong role in promoting transcriptional activity of the reporter gene in gastric cancer cell lines." (PMID 33526057, 2021). "A study shows that the RhoA guanine exchange factor NET1, which is a factor in the metastasis of gastric cancer, isoforming with short 3′ UTR, promotes cellular migration and invasion in vitro, but CFIm25 and metastases in HCC has not been studied." (PMID 29545935, 2018). "We have previously shown that LPA, a phospholipid which acts through G protein coupled receptors and is known to activate RhoA, promotes gastric cancer cell invasion via NET1." (PMID 23945136, 2013). "NET1 has previously been shown to be differentially expressed and functionally important in mediating cancer cell invasion in gastric cancer and in squamous cell skin cancer." (PMID 23945136, 2013). "As expected, knockdown of NET1 resulted in a significant decrease in gastric cancer cell migration, as assed using the in vitro wound-healing assay." (PMID 18827818, 2008). "Lysophosphatidic acid-induced cell invasion and migration were significantly inhibited using either NET1 siRNA or a RhoA inhibitor (C3 exoenzyme), thus indicating the activity of both NET1 and RhoA in gastric cancer progression." (PMID 18827818, 2008). "In this current study, our aim was to further characterise the mechanisms underpinning NET1-mediated gastric cancer cell invasion." (PMID 18827818, 2008). "These cells have been shown to be less migratory and invasive than control cells, suggesting that NET1 mediates gastric cancer cell invasion through cytoskeletal-dependent events." (PMID 18827818, 2008). "Lysophosphatidic acid was shown to increase NET1 mRNA expression in a dose-dependent manner in AGS gastric cancer cells." (PMID 18827818, 2008). "We have previously identified NET1 as being upregulated in GA and to participate in gastric cancer cell proliferation and invasion." (PMID 18827818, 2008). "The functional importance of NET1 in gastric cancer progression was displayed by a suppressive effect of NET1 knockdown on AGS cell migration." (PMID 18827818, 2008). "Loss-of-function experiments were carried out to determine the role of NET1 activity in gastric cancer." (PMID 18827818, 2008). "Expression of Net1 was shown in three separate gastric cancer cell lines, namely AGS, 23132 and KatoIII." (PMID 16552434, 2006). "Invasion is an essential event in the malignancy of gastric cancer and this finding further underpins the role of Net1 in mediating this process." (PMID 16552434, 2006). "It is therefore likely that elevated levels of Net1 in gastric cancers favours tumour proliferation and invasion through RhoA activation." (PMID 16552434, 2006). "siRNA-mediated downregulation of Net1 and Myeov resulted in decreased proliferation and invasion of gastric cancer cells in vitro." (PMID 16552434, 2006). "These functional studies highlight a putative role for NET1 and Myeov in the development and progression of gastric cancer." (PMID 16552434, 2006). "The data presented herein suggest regulatory roles for the in silico identified genes Net1 and Myeov in the setting of gastric cancer." (PMID 16552434, 2006). "mRNA expression determination, using real-time PCR, confirmed elevated Net1 expression in gastric cancer tissue in comparison with normal tissue." (PMID 16552434, 2006). "NET1 has been found to be induced by lysophosphatidic acid (an activator of RhoA) in order to promote cell invasion, cell migration, and cytoskeletal actin organization in gastric cancer." (PMID 33839702, 2021). "In our previous studies LPA activation of RhoA was shown to be mediated via NET1 in gastric cancer." (PMID 23945136, 2013). "Interestingly RhoA, which our group have previously shown to be regulated by NET1 in gastric cancer, has also been shown to activate TGFβ." (PMID 23945136, 2013).
gastric cancer (continued). "We also previously reported LPA to drive the expression of NET1 mRNA in gastric cancer cells." (PMID 23945136, 2013). "Our group have previously shown NET1 to be of functional importance in breast and gastric cancer." (PMID 23945136, 2013). "Net1 and Myeov expression was confirmed in gastric cancer tissue and cell lines." (PMID 16552434, 2006). "The in vitro invasion of AGS gastric cancer cells following Net1 knockdown was also assessed." (PMID 16552434, 2006). "NET1, a RhoA guanine exchange factor, is up-regulated in gastric cancer (GC) tissue and drives the invasive phenotype of this disease." (PMID 21284875, 2011). "Referring to mining of the GEO database, the GSE26309 dataset was divided into AGS gastric cancer cells Control group, RhoA activator group (LPA), RhoA GEF exchange factor (NET1) knockdown group (shNET1), NET1 knockdown and RhoA activator group (shNET1-LPA)." (PMID 37670284, 2023). "Their study further demonstrated that NET1, a regulator of the Rho GTPase pathway, prefers proximal PAS usage in the MKN28 gastric cancer cell line with a high metastatic ability." (PMID 33526057, 2021). "An RNAi approach using an siRNA duplex specifically targeting NET1 mRNA was used to investigate the effect of NET1 knockdown on RhoA activation and AGS gastric cancer cell migration and invasion." (PMID 18827818, 2008). "As well as highlighting the importance of NET1 and RhoA in cell invasion, these data demonstrate that both NET1 and RhoA bioactivities are essential in LPA-induced gastric cancer cell migration and invasion." (PMID 18827818, 2008). "We have previously shown that NET1 is enhanced in gastric cancer tissue in comparison with normal tissue and this study further elucidates the mechanism by which NET1 mediates the progression of the disease." (PMID 18827818, 2008). "Two genes (Net1 and Myeov) not previously studied in gastric cancer were selected for further investigation using an in vitro GA model and a panel of matched ex vivo GA tissue and adjacent normal tissue." (PMID 16552434, 2006). "Net1 was further shown to be expressed in three separate gastric cancer cell lines (Data not shown)." (PMID 16552434, 2006). "Net1 expression in a non-cancerous airway alveolar epithelial cell line (AEC) was less than that in the gastric cancer cell lines." (PMID 16552434, 2006).
hepatocellular carcinoma (9 papers, 2013 to 2024). A malignant tumor that arises from hepatocytes. "To determine if NET1 was differentially expressed in hepatocellular carcinoma, we measured NET1 expression level in hepatocellular carcinoma tissue as well as hepatic cancer cell lines." (PMID 32641699, 2020). "This study aimed at investigating the tumor stiffness of hepatocellular carcinoma (HCC) bearing mice model in vivo to evaluate the therapeutic efficacy of targeting nanobubbles (TNBS) conjugated with NET-1 siRNA (NET-1 siRNA-TNBS)." (PMID 31544556, 2019). "The transfection efficiency of NET-1 siRNA and the apoptotic rate of hepatocellular carcinoma cells were significantly increased when compared with those lacking ultrasound irradiation treatment." (PMID 30126854, 2018). "The NET-1 gene was highly expressed level in SMMC-7721 human hepatocellular carcinoma cell line." (PMID 29423111, 2018). "By activating the Akt-signaling pathway, NET1 promotes hepatocellular carcinoma (HCC) growth and metastasis, and NET1 has been demonstrated to be involved in cell-cycle kinetics by stimulating rRNA synthesis and modulating nucleolar structure." (PMID 38169395, 2024). "However, the role of NET1 in hepatocellular carcinoma (HCC) remains largely uncovered." (PMID 33839702, 2021). "NET1 relates to proliferation, metastasis, and TMN stages of hepatocellular carcinoma (HCC) and can promote the progression of HCC by modulating the PI3K/AKT signaling." (PMID 32420320, 2020).